OR14A2 (olfactory receptor family 14 subfamily A member 2)
Description:
Odorant receptor.
Synonyms: OR5AX1; OR5AX1P
Tractability: Antibody: its Gene Ontology location is reachable by antibodies, with high confidence; UniProt places it where antibodies can reach, with medium confidence; UniProt predicts a signal peptide or a membrane-spanning region.
Gene: Protein-coding gene on chromosome 1 (247,722,957 to 247,748,141, reverse strand). Ensembl gene ENSG00000241128.
Subcellular location: Cell membrane
Pathways (Reactome):
Sensory Perception: Expression and translocation of olfactory receptors; Olfactory Signaling Pathway
Gene Ontology:
Molecular function: odorant binding; olfactory receptor activity; G protein-coupled receptor activity
Biological process: sensory perception of smell; detection of chemical stimulus involved in sensory perception of smell; G protein-coupled receptor signaling pathway
Cellular component: plasma membrane; membrane
Homologues: Orthologues: macaque OR14A2 (94% identical), mouse Or14a258 (73% identical), mouse Or14a259 (72% identical), mouse Or14a260 (72% identical), rat Or14a257b (70% identical), mouse Or14a257 (70% identical), rat Or14a260 (70% identical), rat Or14a257c (69% identical), guinea pig OR14A2 (69% identical), rat Or14a258 (69% identical), mouse Or14a256 (69% identical), rat Or14a257 (68% identical), and 1 more. Paralogues in human: OR14A16 (54% identical), OR14L1 (51% identical), OR14K1 (49% identical), OR14J1 (48% identical), OR14I1 (47% identical), OR14C36 (44% identical), OR5AP2 (42% identical), OR5I1 (41% identical), OR5B12 (40% identical), OR8K3 (40% identical), OR5AS1 (40% identical), OR8K1 (40% identical), and 84 more.
Diseases named in the same sentence as OR14A2 in open-access papers:
OR14A2 is named in the same sentence as 1 disease in open-access papers, as found by Europe PMC text mining. Sharing a sentence is not in itself a finding about the gene and the disease.
OR14A2 shares sentences with these, for which no sentence is quoted: head and neck cancer (1 paper).